SGCG (sarcoglycan gamma)
Description:
Component of the sarcoglycan complex, a subcomplex of the dystrophin-glycoprotein complex which forms a link between the F-actin cytoskeleton and the extracellular matrix.
Synonyms: Gamma-SG; 35DAG; SCARMD2; DAGA4; SCG3; DMDA; TYPE; A4; MGC130048; DMDA1; LGMD2C; LGMDR5; MAM
Tractability: Antibody: its Gene Ontology location is reachable by antibodies, with high confidence; UniProt places it where antibodies can reach, with medium confidence; UniProt predicts a signal peptide or a membrane-spanning region.
Gene: Protein-coding gene on chromosome 13 (23,180,877 to 23,325,165, forward strand). Ensembl gene ENSG00000102683.
Subcellular location: Cell membrane, sarcolemma; Cytoplasm, cytoskeleton
Pathways (Reactome):
Extracellular matrix organization: Formation of the dystrophin-glycoprotein complex (DGC)
Gene Ontology:
Molecular function: protein binding
Biological process: camera-type eye development; cardiac muscle tissue development; heart contraction; muscle organ development
Cellular component: dystrophin-associated glycoprotein complex; endoplasmic reticulum membrane; neuromuscular junction; plasma membrane; sarcoglycan complex; sarcolemma; cytoskeleton; dystroglycan complex; membrane
Genetic constraint (gnomAD): Loss-of-function variants: 21 observed, 24.97 expected, observed/expected ratio (o/e) 0.84, 90% interval 0.6 to 1.21. The upper end of that interval is the gene's LOEUF score, 1.21, which puts it in group 5 of 6, group 1 being the genes least tolerant of losing a copy. Missense variants: 328 observed, 333.17 expected, observed/expected ratio (o/e) 0.98, 90% interval 0.9 to 1.08. Synonymous variants: 138 observed, 123.86 expected, observed/expected ratio (o/e) 1.11, 90% interval 0.97 to 1.28.
Gene-disease validity (ClinGen):
ClinGen rates the evidence that SGCG causes each of these diseases.
autosomal recessive limb-girdle muscular dystrophy (autosomal recessive): Definitive. Autosomal recessive form of limb-girdle muscular dystrophy.
Homologues: Orthologues: chimpanzee SGCG (99% identical), dog SGCG (93% identical), rabbit SGCG (89% identical), guinea pig SGCG (85% identical), rat Sgcg (84% identical), mouse Sgcg (84% identical), macaque SGCG (83% identical), tropical clawed frog sgcg (77% identical), zebrafish sgcg (63% identical), Drosophila melanogaster Scgdelta (38% identical), Caenorhabditis elegans sgn-1 (34% identical). Paralogues in human: SGCZ (58% identical), SGCD (52% identical).
Diseases named in the same sentence as SGCG in open-access papers:
SGCG is named in the same sentence as 54 diseases in open-access papers, as found by Europe PMC text mining. Sharing a sentence is not in itself a finding about the gene and the disease. The quoted sentences say what the papers report.
sarcoglycanopathies (19 papers, 2010 to 2026). "Moreover, LGMD2 has been investigated to be associated with mutations from a group of sarcoglycanopathies genes such as SGCG, SGCA, SGCB, SGCD genes, which cause several subtypes of LGMD2 including LGMD2C to F, respectively." (PMID 36992678, 2023). "In a study performed on 20 Turkish patients, calpainopathy was the most prevalent form, and dysferlinopathy was the least form of LGMDs, and among sarcoglycanopathies, the mutation in the SGCG gene was the most common and in the SGCA gene was the least common form." (PMID 31937337, 2020). "Sarcoglycanopathies are caused by mutations in the SGCA, SGCB, SGCG, and SGCD genes that code for α-, β-, γ-, and δ-sarcoglycan (SG), respectively." (PMID 41009401, 2025). "Sarcoglycanopathies (SGPs) are limb-girdle muscular dystrophies (LGMDs) that can be classified into four types, LGMDR3, LGMDR4, LGMDR5, and LGMDR6, caused by mutations in the genes, SGCA, SGCB, SGCG, and SGCD, respectively." (PMID 39755676, 2025). "Mutations in the α- (SGCA), β- (SGCB), γ- (SGCG), and δ- (SGCD) SG genes cause the four sarcoglycanopathies termed LGMD R3, R4, R5, and R6, respectively." (PMID 40549548, 2025). "Sarcoglycanopathies are caused by mutations which occur in LGMD genes SGCA, SGCB, SGCG, and SGCD that lead to misfolding, truncated, or loss of protein of α, β, γ, and δ protein which stabilizes the sarcolemma of muscle cells." (PMID 40225150, 2023). "Limb girdle muscular dystrophy 5 (LGMDR5, MIM: 253700, formerly LGMD2C), is one of the sarcoglycanopathies caused by pathogenic variations in SGCG." (PMID 36292638, 2022). "Among them are sarcoglycanopathies caused by mutations in at least four genes named SGCA, SGCB, SGCG and SGCD." (PMID 28883879, 2017). "50% of LGMD cases are sarcoglycanopathies related to mutations in SGCA, SGCB, SGCD and SGCG genes, thereby leading to the LGMD2D, LGMD2E, LGMD2F and LGMD2C forms respectively." (PMID 21637626, 2010). "Sarcoglycanopathies (SGPs) are autosomal recessive limb-girdle muscular dystrophies (LGMDs) caused by mutations in four genes: SGCA, SGCB, SGCG, and SGCD, which lead to α-SGP (LGMDR3), β-SGP (LGMDR4), γ-SGP (LGMDR5), and δ-SGP (LGMDR6), respectively." (PMID 39755676, 2025). "Sarcoglycanopathies include four subtypes of autosomal recessive limb-girdle muscular dystrophies (LGMDR3, LGMDR4, LGMDR5 and LGMDR6) that are caused, respectively, by mutations in the SGCA, SGCB, SGCG and SGCD genes." (PMID 34515763, 2022). "Sarcoglycanopathies comprise four subtypes of autosomal recessive limb-girdle muscular dystrophy (LGMD2C, LGMD2D, LGMD2E, and LGMD2F) that are caused, respectively, by mutations in the SGCG, SGCA, SGCB, and SGCD genes." (PMID 30764848, 2019). "Sarcoglycanopathies belong to the group of limb-girdle muscular dystrophies (LGMDs), are inherited autosomal recessively, and result from homozygous or compound heterozygous pathogenic alterations in one of the four sarcoglycan genes, SGCA, SGCB, SGCG, or SGCD." (PMID 36292638, 2022). "The sarcoglycanopathies are a severe form of limb girdle muscular dystrophy caused by mutations in the sarcoglycan genes SGCA, SGCB, SGCG, and SGCD, leading to reduced or absent expression of the alpha-, beta-, gamma-, and delta-sarcoglycan proteins respectively." (PMID 40129306, 2025).
muscular dystrophies (16 papers, 2009 to 2025). "For example, the five top‐ranking candidate genes of patient #13786 that was diagnosed with muscular dystrophy, including the verified disease gene SGCG, were all associated with muscle‐specific processes, such as “muscle contraction” and “muscle organ development” (Dataset EV3D)." (PMID 37232043, 2023). "Screening for the founder c.del521T mutation in SGCG gene may be at the top of diagnosis analysis as this form of severe childhood autosomal recessive muscular dystrophy (SCARMD) is the most frequent muscular dystrophy in Tunisia and that most patients were homozygous for this mutation." (PMID 22908982, 2012). "The remaining six families had pathogenic variants in genes usually associated with muscular dystrophies (HNRNPDL, TOR1AIP1, SGCG, COL6A2, CAV3, TRIP4)." (PMID 38982518, 2024). "An automated process has been developed for the detection of deletions, duplications/insertions and point mutations in any gene or family of genes and has been applied to ten genes known to bear mutations that cause muscular dystrophy: DMD; CAV3; CAPN3; FKRP; TRIM32; LMNA; SGCA; SGCB; SGCG; SGCD." (PMID 19835634, 2009). "We studied the LAMA2 and SGCG genes responsible for the MDC1A and LGMD2C forms of muscular dystrophies, respectively." (PMID 21637626, 2010). "Also, there were no CNVs detected in the targeted analysis of SGCA, SGCB, SGCG, SGCD, and FKRP genes for other frequent limb-girdle muscular dystrophies." (PMID 36425804, 2022).
limb-girdle muscular dystrophy (8 papers, 2016 to 2025). Limb-girdle muscular dystrophy (LGMD) is a heterogeneous group of muscular dystrophies characterized by proximal weakness affecting the pelvic and shoulder girdles. "According to gnomAD, SGCG is tolerant to variation (e.g., loss-of-function (LoF) variation observed/expected=0.84, pLI=0), yet variants in that gene are known to cause limb-girdle muscular dystrophy (OMIM #253700)." (PMID 39285047, 2024).
Duchenne muscular dystrophy (6 papers, 2010 to 2023). Duchenne muscular dystrophy (DMD) is a neuromuscular disease characterized by rapidly progressive muscle weakness and wasting due to degeneration of skeletal, smooth and cardiac muscle. "γ-Sarcoglycan is a dystrophin-associated protein, and loss of function mutations in the SGCG gene produces a clinical picture similar to what is seen in Duchenne muscular dystrophy (DMD)." (PMID 31582396, 2019). "Loss of function mutations in the DMD gene cause Duchenne muscular dystrophy (DMD), while mutations in the SGCG gene, which encodes the dystrophin associated protein γ-sarcoglycan, cause limb-girdle muscular dystrophy type 2C (LGMD 2C)." (PMID 29065150, 2017).
Limb-girdle muscular dystrophy type 2C (4 papers, 2010 to 2023). "Limb-girdle muscular dystrophy type 2C is caused by autosomal recessive mutations in the γ-sarcoglycan (SGCG) gene." (PMID 31582396, 2019). "Limb-girdle muscular dystrophy type 2C (LGMD 2C) is a rare genetic disorder caused by autosomal recessive mutations in the γ-sarcoglycan (SGCG) gene." (PMID 31582396, 2019). "Limb-girdle muscular dystrophy type 2C (LGMD2C) (OMIM # 253700) is an autosomal recessive disorder caused by mutations in the SGCG gene, which encodes γ-sarcoglycan." (PMID 20350330, 2010).
Obesity (2 papers, 2022 to 2023). Accumulation of substantial excess body fat. "Other genes that may play a role in NAFLD and T2D include SGCG, a single-pass transmembrane glycoprotein implicated in the pathogenesis of obesity and T2D in humans." (PMID 37033223, 2023). "To study whether SGCG may be also relevant for human obesity and T2D, we analyzed its expression in human subcutaneous and visceral adipose tissues from both patients with T2D and healthy controls." (PMID 35796564, 2022). "Finally, our expression analysis in human adipose tissue as well as different gWAS indicates that SGCG is also relevant for the pathogenesis of obesity and T2D in humans." (PMID 35796564, 2022). "In humans, mRNA levels of SGCG correlated with body mass index and body fat mass exclusively in diabetic subjects, suggesting that SGCG may present a novel marker for metabolically unhealthy obesity." (PMID 35796564, 2022).
age-related macular degeneration (1 paper, 2012). Age-related loss of vision in the central portion of the retina (macula), secondary to retinal degeneration. "Two of these genes have been related to ophthalmologic disorders, including age related macular degeneration (HMCN1) and keratoconus (VSX1) and several have been related to neurologic disorders (IKBKAP, SGCG, SACS, ARHGEF10, and CACNA1S)." (PMID 23139751, 2012).
anaplastic astrocytoma (1 paper, 2013). "On the other hand, alterations of SGCG, HTR4, ITGB1, CPS1, PROS1 and INPP5A were detected predominantly in anaplastic astrocytoma, while alterations of PDE4D were present in both glioblastoma subtypes." (PMID 24358143, 2013).
astrocytomas (1 paper, 2013). "Our results indicate that alterations of SGCG, PROS1 and ITGB1 genes appeared prevalently in grade III astrocytomas and resulted in shorter survival of patients, implying more aggressive nature of tumors with this genetic signature." (PMID 24358143, 2013).
Asymmetric septal hypertrophy (1 paper, 2021). Hypertrophic cardiomyopathy with an asymmetrical pattern of hypertrophy, with a predilection for the interventricular septum and myocyte disarray. "Our case series included a c.195+4_l95+7delAGTA deletion in intron 2 and c.452_458delTTACTGT deletion in exon 5 of SGCG in a LGMD2C female with mild focal basal septal hypertrophy, asymmetric septal hypertrophy and sinus tachycardia, short PR interval, and incomplete RBBB." (PMID 33567613, 2021).
coronary artery spasm (1 paper, 2021). "Among these DEPs, the protein encoded by the APOA2 transgene affects the development of atherosclerotic lesions in a mouse model, and the SGCG protein decreases coronary artery spasm in mice." (PMID 34418970, 2021).
diabetes (1 paper, 2022). "In addition, another gene SGCG encoding protein in the sarcoglycan complex has been identified for diabetes among Punjabi Sikhs population in India." (PMID 35769078, 2022).
fibrosis (1 paper, 2023). the formation of excess fibrous connective tissue in an organ or tissue in a reparative or reactive process. "Skeletal muscle fibrosis frequently occurs due to an SGCG deficiency-related vulnerability to muscle injury." (PMID 37900130, 2023).
protein deficiency (1 paper, 2024). "Recent preclinical studies in mice have also shown promise for using AAV-based gene transfer therapy to treat LGMD type 2C/R5, which is caused by mutations in the gamma sarcoglycan gene (SGCG) that lead to protein deficiency." (PMID 39110386, 2024).
spastic ataxia (1 paper, 2025). "Additionally, individuals with deletion of the entire SGCG gene also lacked five other genes, among which SACS and MIPEP are reported to cause spastic ataxia and combined oxidative phosphorylation deficiency 31, respectively." (PMID 39755676, 2025).
type 2 diabetes (1 paper, 2015). "Additionally, a variant in the SGCG gene has been associated with type 2 diabetes in Punjabi Sikhs from northern India, but not with type 2 diabetes in non-South Asians or with type 2 diabetes in other ethnic groups from South Asia." (PMID 25930055, 2015).
infection (4 papers, 2022 to 2025). The state of being infected such as from the introduction of a foreign agent such as serum, vaccine, antigenic substance or organism. "ACTA1, typically associated with skeletal muscle actin, and SGCG (Sarcoglycan Gamma), a component of the dystrophin–glycoprotein complex, are often linked to muscle integrity and may indicate cytoskeletal or structural alterations in the kidney post-infection." (PMID 40863220, 2025).
tumor (4 papers, 2007 to 2025). "COL10A1 and SPP1 were upregulated in tumor tissues, and SGCG was downregulated." (PMID 33324550, 2020).
myopathy (3 papers, 2013 to 2022). A disease of the muscle in which the muscle fibers do not function properly. "Several facts suggested that the genetic cause of the myopathy of this patient must lie within the SGCG gene: First, the muscle biopsy showed a lack of γ-sarcoglycan." (PMID 36292638, 2022).
cancer (1 paper, 2019). A tumor composed of atypical neoplastic, often pleomorphic cells that invade other tissues. "For the other four genes (SGCG, CCDC78, OTOP3, and SMPDL3A) in the predicted scoring model, their roles in human cancers have not yet been fully investigated." (PMID 31612869, 2019).
SGCG also shares sentences with these, for which no sentence is quoted: autosomal recessive limb-girdle muscular dystrophies (4 papers); calpainopathy (3); glial tumors (2); glioma (2); Becker muscular dystrophy (1); breast carcinoma (1); cardiac hypertrophy (1); cardiomyopathy (1); CNS tumor (1); colitis (1); colon carcinoma (1); Congenital muscular dystrophy type 1A (1); dermatomyositis (1); dilated cardiomyopathy (1); dysferlinopathy (1); dystrophinopathy (1); ectodermal dysplasia syndrome (1); endometriosis (1); epilepsy (1); facioscapulohumeral muscular dystrophy (1); glioblastoma (1); helminth infection (1); hereditary spherocytosis (1); keratoconus (1); laminopathy (1); melanoma (1); neurologic disorders (1); optic atrophy (1); Pompe disease (1); prostate carcinoma (1).
A further 4 diseases each share a sentence with SGCG in 1 paper.